CASP9 (caspase 9)
Diseases named in the same sentence as CASP9 in open-access papers (continued):
Sharing a sentence is not in itself a finding about the gene and the disease.
tumor (continued). "There was however a non-significant trend towards patients with tumours expressing low levels of caspase-9 protein having a worse RFS, which may reflect the importance of caspase-9 as an effector molecule of apoptotic cell death following treatment with current therapeutics." (PMID 25157404, 2014). "Among them, 6 genes including BCL2, BCL2L11, BAD, CASP7, CASP9, and CYCS expression reduced in tumor tissue compared to normal according to meta-analysis studies and RNA-seq TCGA data." (PMID 33292233, 2020). "Consistently, we identified a negative correlation between tumour angiogenesis, as corroborated by VEGF levels, and cell death as verified by caspase-9 levels." (PMID 31836811, 2019). "In the same direction, and given that we have found similar amounts of complex caspase-9/PP2A in healthy and tumour cells (data not shown), it is exciting to understand how the peptide specifically recognizes tumour and no healthy cells." (PMID 23637769, 2013). "The TUNEL staining assay indicated that the blockages of P2X7 and especially caspase-8 could significantly inhibit the apoptotic process induced by the cryoablated tumor extracts in GL261 cells, while caspase-9 blockage did not affect the apoptosis-triggering effects of these extracts." (PMID 24818132, 2014).
infection (155 papers, 2002 to 2026). The state of being infected such as from the introduction of a foreign agent such as serum, vaccine, antigenic substance or organism. "Although effects in A549 cells were masked by unexpectedly high baseline caspase-9 cleavage in uninfected cells, western blot trends nevertheless indicate an underlying caspase-9-mediated apoptosis over the course of infection with either virus." (PMID 40896365, 2025). "Activated CASP9 (~39–37 kDa) levels were also detected, indicating that this mitochondrial cell-death-associated caspase was engaged during ∆M36 infection, even though mitochondrial BCL2-family proteins were dispensable for the death." (PMID 34578288, 2021). "Furthermore, infection led to the loss of mitochondrial membrane and activation of caspase-9, highlighting the intrinsic pathway's importance in activating NDV-mediated apoptosis." (PMID 37720338, 2023). "Infections with virulent Salmonella and Listeria increased the signal intensity of cleaved Parp1 (rather weak for Lm), activated caspase-9 and caspase-7 already after 5 h and displayed full activation (compared to staurosporine, STS) after 16 hours." (PMID 39885151, 2025). "Studies have shown that LPS infection enhanced the expression of Caspase-3, Caspase-8, Caspase-9, and BAX genes and proteins while reducing the levels of BCL-2 gene expression and protein abundance." (PMID 40136393, 2025). "Time course studies of rVSV infection pointed to a consecutive activation of intrinsic MOMP-caspase-9 signaling, as well as caspase-8-mediated extrinsic apoptosis, both leading to caspase-3/7 effector functions." (PMID 40896365, 2025). "At 4 h post-infection, cells in late or early apoptotic stages and caspase-9 activity were reduced in infected cells compared with uninfected cells." (PMID 40003058, 2025). "At 24 to 120 h after infection, T0 cells displayed increased caspase-9 activity compared to group C (p < 0.01)." (PMID 40003058, 2025). "After 4 h of infection, T0 showed lower levels of caspase-9 activity compared to group C (p < 0.01)." (PMID 40003058, 2025). "Our analysis revealed significant upregulation of key apoptosis-related genes, including caspase-7 (P = 0.022), caspase-8 (P = 0.0003), and caspase-9 (P = 0.0003), in response to infection." (PMID 41048496, 2025). "Infection with Helicobacter pylori can promote the activation of CASP9 in B cells, thereby influencing the immune response." (PMID 41551593, 2025). "Executioner caspase activity is robustly activated in HeLa cells upon infection with virulent Lm, presumably via the intrinsic pathway and the activation of caspase-9." (PMID 39885151, 2025). "The inhibition of caspase-3 and caspase-9 significantly enhanced host cell viability during late infection, coinciding with the termination of Rh-B8 replication." (PMID 40607949, 2025). "We observed that, in the case of 14-3-3η siRNA-treated cells, major components of the innate immune system, such as MDA5–MAVS–caspase 9–caspase 3 stem, and their induced expression are delayed or modulated after 24 h of infection." (PMID 41157608, 2025). "In the in vivo zebrafish model, we showed that neutrophils undergo Casp3- and Caspase-9-dependent apoptosis during ST infection, indicating that the intrinsic apoptotic pathway is engaged, a process not observed in macrophages." (PMID 41360763, 2025). "Autophagy induction was also shown to enhance cell survival later in infection and reduced caspase-9 expression, which indicates lower levels of apoptosis." (PMID 40042894, 2025). "CASP9 was differentially up-regulated after 3 and 4.5 h post infection (2.2 and 1.9-fold up-regulation, respectively)." (PMID 35573800, 2022). "DTMUV infection triggers typical lesions of apoptosis, and caspase-8 and caspase-9 are involved in DTMUV-induced apoptosis." (PMID 35799206, 2022).
infection (continued). "When C6/36 cells were treated with double-knockdown of IAP and GST, respective increases of up to 2.6- and 2.83-fold in caspase-9 and -3 during infection for 48 hpi were detected." (PMID 33807863, 2021). "Cleaved/activated caspase-9 increased after EV-A71 infection from 24 to 72 hrs p.i. in both cell lines." (PMID 33481814, 2021). "We also documented a significant increase in caspase 9 expression notably after 72 h infection in highly infected cell-derived EVs." (PMID 34926703, 2021). "The mRNA expression of caspase-3, caspase-9 and cyt-c in bMECs significantly increased with duration of infection time, implying apoptosis was triggered by K. pneumoniae." (PMID 33468111, 2021). "Here, we found that MO infection remarkably increased intracellular ROS levels in a time-dependent manner and significantly upregulated transcriptional levels of Bax, caspase-9, and caspase-3 genes." (PMID 34678131, 2021). "We also found that caspase 3 and caspase 9 were decreased upon hypoxia induction both in vitro and in vivo, which were partially reversed by C75 treatment or shFAS infections." (PMID 34457121, 2021). "The expression level of the Caspase-9 gene in the liver of fish in 4‰ treatment was significantly higher than that in fish in 0.5 and 8‰ treatments before infection and at 24 and 48 hpi." (PMID 34305652, 2021). "For caspase-9, activity in WT-infected cells was significantly lower than in 65ST-infected cells after 3 and 5 h post-infection." (PMID 33114369, 2020). "In this study, we found that caspase-3, caspase-8 and caspase-9 activity was significantly higher in the infection groups than in the mock group at 2 h, 4 h, 6 h, and 8 h (P < 0.001), indicating that apoptosis was activated in the infected macrophages." (PMID 32517648, 2020). "Our results show that the infection-mediated increase in cleaved caspase-9 and caspase-3 levels is overall higher in PBMO, whereas exclusively in CBMO, EGFR inhibition increases the infection-mediated cleavage of both caspases." (PMID 32082070, 2019). "It was also noteworthy that like the effect of caspase-9 and caspase-3, the provoked cleavage of them was prevented during the infection course (P < 0.05)." (PMID 31534118, 2019). "From 12h to 72h post-infection, the levels of Caspase-3, Caspase-9 and Bax proteins, and Bax/Bcl-2 protein ratio in the lean-E." (PMID 31085802, 2019). "After infection, large numbers of positive caspase-9 were visualized in the neutrophil-infiltrated areas or the alveolar wall in the lean- and DIO-E." (PMID 31772700, 2019). "Following a 5 h infection, HeLa cells were harvested and assessed for caspase-9 activation by Western blotting." (PMID 30232373, 2018). "To evaluate the activation of apoptosis without HAX-1, we infected HAX-1kd and HAX-1wt cells with H9N2 (wt) virus at an MOI of 1 and analyzed the cleavage status of caspase-9 and caspase-3 during the course of infection." (PMID 29576744, 2018). "The expression levels of apoptosis-related proteins were examined by Western Blot; caspase-3, caspase-8, and caspase-9 activation and Bcl-2/Bax levels in A549 cells were assessed following infection with rL-RVG or NDV and treatment with MLA and ACB." (PMID 28974241, 2017). "Following grass carp reovirus (GCRV) stimulation in vivo, Bid and apoptosis related genes Caspase-9 and Caspase-3 was up-regulated significantly at the late stage of infection." (PMID 29100321, 2017). "Cleavage of caspase-12 and caspase-9 gradually increased in a time-dependent manner over a 48 h period, while caspase-3 started to decrease by 24 h post infection (pi)." (PMID 28018864, 2016). "We found increased caspase-9 and caspase-3 cleavage in MS_PPE32 infected macrophages in infection comparison with control group." (PMID 27634911, 2016).
infection (continued). "Western blot analysis showed that full-length procaspase-3 decreased in the B.suis.S2 infection group at 24 h post-infection, whereas caspase-9 and caspase-8 increased in the B.suis.S2 infection group at 24 h post-infection." (PMID 26904517, 2016). "We found increased caspase-1 expression in PPE32-incubated or MS_PPE32-infected macrophages in comparison with control group, and the cleaved caspase-9 and caspase-3 were enhanced after MS_PPE32 infection." (PMID 27634911, 2016). "In our study, the expression of caspase-9 was significant in 5b WT-infected PAMs 1 h post-infection, indicating that Adh mediates caspase-9 activation and rapid mitochondrial membrane potential changes in the early phase of A. pleuropneumoniae infection." (PMID 27046446, 2016). "The activation of caspase-3 and intrinsic apoptosis-related protein caspase-9 were down-regulated in IFI6+/+ but up-regulated in IFI6-/- cells at 24–48 hrs post-infection." (PMID 26244642, 2015). "For the periods evaluated, activation peaks at 18 or 14–18h post-infection for caspase-8 and caspase-9, respectively." (PMID 26513474, 2015). "The higher levels of activated caspase-9 in the infected apaf-1−/− MEFs compared to the infected control MEFs (approximately 5 times) is due to a higher infection rate in the apaf-1−/− MEFs." (PMID 26290316, 2015). "We evaluated caspase-9 protease activity in host cell cytosolic fractions after infection of apaf-1−/− MEFs." (PMID 26290316, 2015). "In A172 cells, activation of caspase 8 and caspase 9 was noted at 12 h post-infection, and caspase 3 at 36 h post-infection." (PMID 25350381, 2014). "We found that A172, SK-N-SH and RD cells shared the same apoptotic pathways, with caspase 3, caspase 8 and caspase 9 all being activated after CA16 infection." (PMID 25350381, 2014). "In the initial period of infection, the ureaplasmal isolates increased caspase 9 gene expression in HEp-2 cells." (PMID 25299837, 2014). "Ad5/F35-XAF1 infection consistently induced the cleavage of caspase-9, 8, 3 and PARP and the release of mitochondrial cytochrome c into the cytosol in dose- and time-dependent manners." (PMID 24980821, 2014). "The activation of caspase 8, in addition to caspase 3 and caspase 9, was investigated in response to infection with EV71." (PMID 25350381, 2014). "After CA16 infection, caspase 8 and caspase 9 activities first increased and then decreased from 36 h post-infection in RD and SK-N-SH cells or from 24 h post-infection in A172 cells." (PMID 25350381, 2014). "The activated cleaved fragments of caspase 9 were detectable at 12 h after infection and significantly higher at 24 h after infection in IAV-infected cells than in mock-treated cells." (PMID 24923273, 2014). "Using antibodies that recognize caspase-9/3, we performed western blotting to detect procaspase-9/3 expression of Lovo cells’ post infection with WT and ΔespF strains." (PMID 23372831, 2013). "Quantitative results showed that caspase-9 had significantly increased by 36 hpi in GST-knockdown C6/36 cells after infection; however, it decreased after treatment with L-NAC." (PMID 22530071, 2012). "Apoptosis occurred and proceeded through the course of the infection, as we observed cleaved/activated caspase-9 as well as the emergence of downstream executioner caspases-6, -7, and -3, which eventually destroyed the infected swine macrophages." (PMID 22279582, 2012). "We then tested if infection also affects signaling upstream of the executioner caspase i.e. caspase-9 and caspase-8 processing or activity, respectively." (PMID 21799887, 2011). "Further analyses demonstrated that upregulation of cleaved caspase-8 and Bcl-2 expression was minimal, but expression levels of cleaved caspase-9, Bax and cytoplasmic cytochrome C increased in both cells after the infection." (PMID 21952623, 2011).
infection (continued). "Examination of host cell death prior to this extensive cell loss (4 h post infection) revealed that WT EPEC infection was linked to low levels of necrosis (assessed by trypan blue) and apoptosis (assessed by caspase-9 cleavage)." (PMID 20345487, 2010). "A 6.6-fold increase of active caspase-9-positive cells was found after RML6 infection of Bos2 cells and a 11.4-fold increase in persistently prion-infected N2A cells compared with Bos2 cells." (PMID 17573907, 2007). "In the HCT116 PUMA+/+ cell line, caspase-9 activity was induced 3.0 fold after 48 hours of Ad-E2F-1 infection." (PMID 17263886, 2007). "In HCT116 PUMA-/- cells, caspase-9 activity was also increased after Ad-E2F-1 infection, but to a lesser degree (1.5 fold after 48 hours of Ad-E2F-1 infection)." (PMID 17263886, 2007). "Positive cells for active caspase-9 were also found after RML6 infection of Bos2 cells and after treatment of these cells with either BAY117082 or staurosporine." (PMID 17573907, 2007). "The expression level of endogenous caspase-9 in U251 and U-373MG cells was much lower than that of exogenous caspase-9 induced by Adv-Casp9 infection." (PMID 11870542, 2002). "The infection activates caspase-9 and caspase-3, but not caspase-8, and causes mitochondrial damage, indicating apoptosis via the mitochondrial pathway." (PMID 41701783, 2026). "Caspase-9 activity gradually decreased throughout the infection." (PMID 40003058, 2025). "qRT-PCR analysis revealed that gcHnf4α overexpression upregulated the mRNA levels of apoptosis-related genes—aif, caspase 3, caspase 8, caspase 9, bax, and bcl-2—during A. salmonicida mono - infection, indicating potential engagement of both pro- and anti-apoptotic pathways." (PMID 40920830, 2025). "In E. tenella infection of primary epithelial cell cultures, the apoptotic response, including cytochrome c release and caspase-9 activation, peaks at 96 to 120 h post-infection, which coincides with the rupture of second-generation schizonts and the onset of hemorrhagic lesions in vivo." (PMID 40003058, 2025). "Inhibition of caspase-9 activity significantly enhanced host cell survival up to 96 hours post-infection (hpi), supporting the hypothesis that mitochondrial stress-induced caspase-9 activation is a key driver of late-stage apoptosis during Rh-B8 infection." (PMID 40607949, 2025). "The results shown that the expression of proapoptotic proteins, including Bax, caspase-3, caspase-9 and cytochrome c, increased in the infection group; however, the expression of the antiapoptotic protein Bcl-2 decreased, indicating that apoptosis was induced by GoAstV infection in GEK cells." (PMID 39502173, 2024). "Notably, cleavage of caspase-3 significantly increased 48 h post-infection, while caspase-9 activation commenced 24 h post-infection, suggesting that mitochondrial damage plays a pivotal role." (PMID 39364165, 2024). "Similarly, Caspase 9 activity increased by over 92% in HIV-1 infected cells compared to mock infection." (PMID 39507335, 2024). "In addition, the protein expression levels of Bax, cleaved caspase-3, cleaved caspase-9 and Cytc increased significantly from 12 hpi to 48 hpi in the infection group." (PMID 39502173, 2024). "ST7 infection causes a reduction in the activity of caspase 3 and caspase 9, but not caspase 8 after 6 and 12 h of infection." (PMID 39338600, 2024). "In addition, compared with their respective control groups, the PRV infection group showed a significant up-regulation of Caspase-9 at the 96 hpi post-infection time point." (PMID 38155259, 2023). "The involvement of caspases 8 and 9 was also investigated and no significant changes over time for caspase 8 were observed, while caspase 9 was cleaved starting at 24 h post-infection (a decrease in constitutive form of caspase at 48 and 72 h after infection was observed)." (PMID 38087282, 2023).